ADAM8 (ADAM metallopeptidase domain 8)
Diseases named in the same sentence as ADAM8 in open-access papers (continued):
Sharing a sentence is not in itself a finding about the gene and the disease.
tumor (continued). "Similarly, high ADAM8 expression has been detected in multiple other solid tumors, i.e., lung, liver, pancreas, stomach, colon, bone, head and neck, and associated with either poorer prognosis, more metastatic phenotype or higher tumor grade." (PMID 37568162, 2023). "Based on numerous previous studies, ADAM8 plays a crucial role in promoting tumor cell migration and invasion in various cancers, and the profound effect of its cytoplasmic domain on intracellular signaling in PDAC is demonstrated here." (PMID 39412616, 2025). "ADAM8 hydrolyzes a variety of protein components in the ECM to help tumor cells enter the blood circulation." (PMID 40092702, 2025). "ADAM8 can also release growth factors acting on tumor cells and promote the proliferation and migration of tumor cells." (PMID 40092702, 2025). "In TNBC mouse models, an ectodomain antibody against ADAM8 was reported to decrease primary tumour growth, inhibit metastasis formation, and reduce the size of existing metastases, suggesting a new therapeutic approach for TNBC." (PMID 40427200, 2025). "In the KRAS-mutant group, ADAM8 expression appeared to be elevated in the KRAS-mutant tumor group compared to the KRAS wild-type tumor group." (PMID 39329961, 2024). "ADAM8, being an extracellular matrix protease, can be regulated by these pathways, leading to its elevated expression in the KRAS 12/13-mutated tumor group." (PMID 39329961, 2024). "Evidence suggests that ADAM8 positive tumor cells accumulate in the invasive zone of the tumor and its expression is maintained during metastasis." (PMID 38317965, 2024). "Previously, we identified the cell surface protein A Disintegrin And Metalloprotease 8 (ADAM8) as a driver of TNBC tumor growth and spread via its metalloproteinase and disintegrin (MP and DI) domains." (PMID 38675197, 2024). "Elevated Adam8 levels are associated with increased serum Alpha-fetoprotein (AFP), advanced tumor stage, poor differentiation, increased tumor recurrence and metastasis, and reduced survival." (PMID 37370863, 2023). "Previous studies incorporating MDA-MB-231 Adam8 KO mouse xenograft models showed the presence of significantly smaller tumors, decreased levels of circulating tumor cells, and lower numbers of brain metastases." (PMID 37370863, 2023). "On the other hand, the decrease in membrane-bound PD-L1 would diminish the ability of tumor cells in ADAM8-high regions to compromise local lymphocyte attack." (PMID 38139457, 2023). "Such an ADAM protease is ADAM8, which has been proven to exhibit tumor-supportive activities when expressed in cancer cells, thereby promoting cancer progression, invasion, and enhancing immune cell enrolment." (PMID 36910158, 2023). "Based on these results, however, molecular data suggest that ADAM8 has a systemic effect in the tumor microenvironment and that its expression in different cell types needs to be taken into account for the specific treatment ADAM8 in cancers." (PMID 36910158, 2023). "High expression of ADAM8 correlates with the size of the primary tumor, vascular invasion or the presence of metastases in lymph nodes, by affecting the level of p-ERK kinase." (PMID 37185715, 2023). "The metalloprotease-disintegrin ADAM8 is highly expressed in GBM tumor and immune cells and correlates with poor survival." (PMID 35371977, 2022). "In our experiments, miR-181a-5p enriched vesicles were taken up by naive U87 cells demonstrating a role for ADAM8 in the tumor microenvironment." (PMID 35371977, 2022). "Generation of stable ADAM8 KO clones with subsequent miRNA screening revealed that the tumor suppressor miRNA miR-181a-5p shows a significantly higher expression in GBM cells deficient in ADAM8." (PMID 35371977, 2022). "ADAM8 as a multidomain enzyme exhibits numerous tumor-supporting characteristics by promoting invasion, angiogenesis, and chemoresistance in GBM." (PMID 35371977, 2022).
tumor (continued). "In recent studies, A disintegrin and metalloprotease 8 (ADAM8) was identified as an extracellular metalloprotease-disintegrin important for tumor progression, invasion, and metastasis in pancreatic ductal adenocarcinoma (PDAC)." (PMID 35216088, 2022). "In the current study, we analyzed EV release from PDAC cells and the cellular interactions between macrophages and PDAC tumor cells in an ADAM8-dependent manner." (PMID 35216088, 2022). "One such ADAM protease is ADAM8, a metalloprotease-disintegrin with a proven record of tumor-supporting effects when expressed in tumor cells, thereby facilitating tumor progression, invasion, and immune cell recruitment." (PMID 35216088, 2022). "From these data, we conclude that ADAM8 has a systemic effect in the tumor microenvironment, and its expression in distinct cell types has to be considered for ADAM8 targeting in tumors." (PMID 35216088, 2022). "A disintegrin and metalloprotease 8 (ADAM8) is a member of the ADAM family which is involved in tumour development by enhancing cellular abilities of invasion and migration, stimulating angiogenesis and inhibiting cancer cell apoptosis." (PMID 35565436, 2022). "Among these, the tumor suppressor miR-181a-5p was significantly upregulated in ADAM8 knockout clones." (PMID 35371977, 2022). "The changes in tumor volumes showed that ADAM8 knockdown significantly reduced the tumor growth under TMZ treatment." (PMID 36230833, 2022). "Proliferation was not affected when comparing control with KO 1 cells, whereas invasion was significantly reduced upon ADAM8 deficiency, suggesting that, similar to previous results, ADAM8 has a strong effect on cellular motility in tumor cells." (PMID 35216088, 2022). "EVs were isolated from MB-231 and Panc89 tumor cells ± ADAM8, and their protein cargo was analyzed by Western blot." (PMID 35216088, 2022). "Taken together, we provide evidence for a functional axis involving ADAM8/miR-181a-5p/MAPK/MMP9 in GBM tumor cells." (PMID 35371977, 2022). "RT-qPCR experiments were conducted on 22 tumor tissue samples from patients admitted to our clinical department to analyze the expression profiles of ADAM8, MMP9, and miR-181a-5p in GBM tissue." (PMID 35371977, 2022). "Consistent with the observed effects on tumor growth in vivo, ADAM8 knockdown markedly prolonged the overall survival of tumor-bearing mice." (PMID 36230833, 2022). "Positive ADAM8 expression was more frequent in GC tissues in comparison to normal tissues and correlated with tumour size (T factor), N (nodal involvement), vessel invasion as well as shorter GC patient overall survival." (PMID 35565436, 2022). "In PDAC, a significant contribution of ADAM proteases to tumor progression was reported for ADAM8, ADAM9, ADAM10, ADAM12, and ADAM17." (PMID 33578644, 2021). "In fact, among these ADAMs, ADAM8 has been reported to be overexpressed in various other human tumours." (PMID 33314720, 2021). "By analyzing ADAM8 expression in neutrophils, we were able to show that an increased number of ADAM8-positive neutrophils particularly in venules of the tumor areas can be of prognostic value for PDAC patients." (PMID 33578644, 2021). "We identified ADAM8-positive cells not only in the duct-like structures of the tumor area, but also in the tumor microenvironment." (PMID 33578644, 2021). "Due to high expression levels in PDAC tumor cells, ADAM8 was previously identified as a potential therapeutic target in PDAC." (PMID 33578644, 2021). "More generally, our data provide evidence for an EV based communication in the PDAC tumor microenvironment that can be triggered in the pro-oncogenic direction by the presence of ADAM8." (PMID 34368146, 2021). "Given a distinct physiological expression profile of ADAM8 in immune cells such as macrophages and leukocytes, an ADAM8 expression in stromal cells of PDAC is likely and suggests an important role of ADAM8 in the tumor microenvironment of PDAC." (PMID 33578644, 2021).
tumor (continued). "We found that varying grades of tumor were significantly correlated with 6 ADAMs, including ADAM8/10/12/15/19/TS12." (PMID 33062410, 2020). "The result was consistent with another study in which Yang et al7 concluded that patients with ADAM8‐positive tumours had worse 5‐year disease‐free survival and overall survival." (PMID 32954649, 2020). "Early reports have indicated that ADAM8 also promotes cancer development and metastasis in a variety of tumor types." (PMID 32976115, 2020). "Significantly, treatment with an anti-ADAM8 antibody targeting its extracellular MP and DI domains reduced primary tumor burden and metastases in mice." (PMID 27039296, 2016). "After 3 weeks, anti-ADAM8 treatment had significantly decreased primary tumor burden by approximately 50% and tumor weight by approximately 36%." (PMID 24375628, 2014). "In a multivariate analysis that included tumor size, tumor grade, lymph node status and ER status, ADAM8 mRNA level was found to be an independent predictor of poor disease-free ( P = 0.001) and overall survival ( P = 0.052)." (PMID 24375628, 2014). "As a positive correlation was identified between ADAM8 and CD31 mRNA levels in basal-like tumors, high ADAM8 levels appear associated with increased tumor vascularization in these patients." (PMID 24375628, 2014). "Using both knockdown and antibody targeting strategies, ADAM8 was shown to promote TNBC tumor growth, angiogenesis, spread of CTCs and metastatic dissemination in orthotopic mouse models." (PMID 24375628, 2014). "In vivo, treatment with an anti-ADAM8 antibody from the time of cell inoculation reduced primary tumor burden and metastases." (PMID 24375628, 2014). "ADAM8 also activates β1-integrin on the tumor cells permitting their attachment to the vascular endothelium and entry into the blood circulation." (PMID 24375628, 2014). "Although we explored the expression status, potential roles and clinical implications of ADAM8 in CRC, the underlying mechanism by which ADAM8 influences tumor cell growth and postoperative survival of CRC patients was not investigated in this study." (PMID 25098630, 2014). "Among the 24 CRC patients with ADAM8 positive tumor tissues, high and moderate expression of ADAM8 was detected in 20 cases and weak expression in 4 cases." (PMID 25098630, 2014). "The data demonstrated that patients with high ADAM8 expression in the tumor have worse survival rates." (PMID 22369429, 2012). "In this current study we wanted to identify the prognostic value of ADAM8 serum and tumor levels in HNSCC." (PMID 22369429, 2012). "We found that elevated serum levels of ADAM8 corresponded with high expression of ADAM8 in tumor samples (p-value = 0.011, Jonckheere Terpstra = 4380)." (PMID 22369429, 2012). "Rather, it is likely that the ADAM8 cytoplasmic domain could exert a prominent role for PDAC tumor progression." (PMID 39412616, 2025). "Thus, ADPs were next tested in a single-dose pre-existing orthotopic ADAM8+ MDA-MB-231 TNBC cell line-derived primary tumor growth model." (PMID 38675197, 2024). "Interestingly, the administration of anti-ADAM8 treatment to pre-existing tumors followed by a maintenance treatment for a duration of 5 weeks after tumor resection on day 15 exhibited a remarkable reduction in the metastatic capacity." (PMID 38317965, 2024). "By administering intra-peritoneal injections of 0.5 mg/kg anti-ADAM8 antibody twice a week after tumor cell implantation in the mammary fat pad, substantial reductions were observed in the primary tumor size and burden, as well as in the number and size of brain metastases." (PMID 38317965, 2024). "Therefore, the observed associations between the expressions of the SEMA7A, SEMA4D, ADAM8, and ADAMTS10 in tumor groups with KRAS, NRAS, BRAF, PIK3CA, and AKT mutations require validation in larger study cohorts." (PMID 39329961, 2024).
tumor (continued). "Based on these outcome, it can be speculated that ADAM8 could also perform a functional task within immune cells of the tumor microenvironment." (PMID 36910158, 2023). "Furthermore, knockdown and antibody targeting strategies in TNBC orthotopic mouse models showed ADAM8 promotes both tumor growth and spread." (PMID 37568162, 2023). "Meanwhile, a disintegrin and metalloproteinase 8 (ADAM8) was another gene related to enzyme production and could promote tumor metastasis probably through the degradation of ECM components." (PMID 36816030, 2023). "In GBM cells, ADAM8 modulates angiogenesis thereby affecting GBM tumor progression." (PMID 36230833, 2022). "Considering ADAM8 as a protein that plays an important role in both CNS inflammation and tumor pathology, we reasonably believe that ADAM8 may mediate the malignant biology of tumor cells through enhancing or maintaining local inflammatory responses in GBM." (PMID 36230833, 2022). "Given the strong endogenous expression of ADAM8 in macrophages, we hypothesized that ADAM8 serves important functions in tumor cell–macrophage interactions." (PMID 35216088, 2022). "A cell-autonomous effect of ADAM8 in tumor cells was extensively described in numerous studies." (PMID 35216088, 2022). "Considering that miR-181a-5p is a tumor suppressor miRNA in GBM, ADAM8 dependent silencing of miR-181a-5p could further contribute to tumor progression." (PMID 35371977, 2022). "Furthermore, high expression of ADAM8 has been reported in various tumor types and is related to invasiveness and poor prognosis." (PMID 36506313, 2022). "Under malignant conditions, ADAM8 is highly expressed and could play an important role in cell–cell communication as expression has been observed in tumor and immune cells of the tumor microenvironment (TME) such as macrophages." (PMID 35216088, 2022). "From all tumor patients, paraffin-embedded sections were stained and scored for ADAM8 expression." (PMID 33578644, 2021). "Furthermore, we found that increasing ADAM8 expression renders the tumour cells more resistant against apoptosis." (PMID 33314720, 2021). "Likewise, decreased levels of metalloproteinase MMP9 and ADAM8 also shrank tumor progression on this basis." (PMID 34298635, 2021). "Mechanistically, this observation could point towards a detrimental effect of ADAM8-positive neutrophils in PDAC by regulating neutrophil transmigration from the vasculature to the tumor site." (PMID 33578644, 2021). "Interestingly, ADAM8 expression was detected at the leading front of microinvasive areas at primary tumor sites." (PMID 24375628, 2014). "Consistently, strong ADAM8 staining was detected around the necrotic areas in shCtrl-3 tumors, but absent in tumors derived from shA8-20 cells, even though the extent of necrosis was similar in both tumor populations." (PMID 24375628, 2014). "Two essential novel roles for ADAM8 in tumor progression were identified." (PMID 24375628, 2014). "Consistently, both ADAM8 antibody treatment and KD reduced tumor angiogenesis." (PMID 24375628, 2014). "This suggests a lower potential risk for developing metastases to distant organs when ADAM8 is knocked down, independent of tumor size." (PMID 24375628, 2014). "Thus, ADAM8 promotes tumor cell adhesion onto and migration through an endothelial cell layer, as found in a vessel wall." (PMID 24375628, 2014). "We found that high ADAM8 serum levels correlated with high ADAM8 expression in tumor samples." (PMID 22369429, 2012). "Therefore we investigated ADAM8 serum levels and tumor expression in tumor patients and correlated the results to patients' clinical data." (PMID 22369429, 2012). "In summary tumor ADAM8 expression is a prognostic marker for survival in contrast to serum levels." (PMID 22369429, 2012). "Our study was the first to compare serum and tumor levels of ADAM8 in the same patients with HNSCC." (PMID 22369429, 2012).
tumor (continued). "Using commercially available reagent-grade anti-ADAM8 Abs, we showed proof-of-concept that dual MP and DI inhibitory Abs can be isolated, and using one such inhibitor demonstrated efficacy against both primary tumor growth and metastasis; the mechanism driving dual inhibition was not elucidated." (PMID 38675197, 2024). "Consequently, ADAM8 could be a major player for the communication of tumor cells with the tumor microenvironment, in particular in conjunction with TAMs." (PMID 36230833, 2022). "In tumorcells, ADAM8 is involved in invasion, migration, and angiogenesis.The use of bivalent inhibitors could impair migration and invasionthrough the double binding to a homodimeric form of ADAM8 locatedon the cell surface of tumor cells." (PMID 35111280, 2021). "Elevated ADAM8, ADAM9, ADAM12 and ADAM17 levels were observed in CRC tissues and correlated with more advanced tumor stage, while increased serum ADAM15 concentrations associated with the presence distant metastases." (PMID 41976350, 2026). "Published data show that several ADAMs, including ADAM8, ADAM9, ADAM10, ADAM12, and ADAM17, are overexpressed in tumours." (PMID 40427200, 2025). "We subsequently investigated the potential associations between the expression levels of SEMA7A, SEMA4D, ADAM8, and ADAMTS10 proteins and the characteristics of tumor size (T), lymph node involvement (N), metastasis (M), and disease stage." (PMID 39329961, 2024). "The ADAM8 Metalloproteinase (MP) domain promoted release of various factors (e.g., VEGF-A, PDGF-AA, angiogenin) from the tumor cell surface that mediate angiogenesis and tumor growth." (PMID 37568162, 2023). "In contrast, mean ADAM8 and MMP9 expression levels were upregulated in the investigated tumor samples." (PMID 35371977, 2022). "Analysis of patient tissue samples (n=22) revealed that in GBM, miR-181a-5p is strongly downregulated compared to ADAM8 and MMP9 mRNA expression, even in localized tumor areas." (PMID 35371977, 2022). "From our data, there are some indications that LCN2 can lead to enhanced activation of pro-MMP-9, thereby causing a higher degree of extracellular proteolysis, leading to the tumor-promoting effect of positive co-regulation of MMP-9 and LCN2 by ADAM8." (PMID 35216088, 2022). "Analysis of tumor edge (L2 and L3) and core tumor (L4) with strongly proliferating and vascularized zones revealed reversed expression patterns for MMP9, ADAM8, and miR-181a-5p." (PMID 35371977, 2022). "When tumor cells were co-cultured with macrophages (THP-1 cells), expression of LCN2 and MMP-9 in ADAM8 KO cells was induced, suggesting that macrophage signaling can overcome ADAM8-dependent intracellular signaling in PDAC cells." (PMID 35216088, 2022). "ADAM8 and epithelial‐mesenchymal transition (EMT) play an important role in tumour invasion has been well established." (PMID 32954649, 2020). "ADAM8 facilitates the release of pro-angiogenic factors, including VEGF-A, into the tumor microenvironment, leading to neovascularization and continued tumor growth." (PMID 24375628, 2014). "Furthermore, our investigation revealed a notable upregulation of several matrix metalloproteinases (MMPs) in tumor-infiltrating macrophages, including MMP9, MMP12, MMP19, ADAM8, ADAM9, and ADAM17." (PMID 38254761, 2024). "ADAM8 was significantly highly expressed in tumour tissue compared with para-cancerous tissue in all types of cancer, except for KIRC, PRAD, and THCA, indicating ADAM8 could be a significant biomarker for tumours." (PMID 37082201, 2023). "Furthermore, the angiogenic potential of ADAM8 in primary macrophages was mediated by the regulation of osteopontin (OPN), a crucial inducer of tumor angiogenesis." (PMID 35600367, 2022). "ADAM8 as an inflammatory mediator regulates diverse pathological processes in CNS inflammation and tumor biology through its proteolysis and non-proteolysis function, attributable to the different structural domains present in the full-length protein." (PMID 36230833, 2022).